TNC (tenascin C)
Diseases named in the same sentence as TNC in open-access papers (continued):
Sharing a sentence is not in itself a finding about the gene and the disease.
breast cancer (continued). "On the other hand, tenascin-C, produced by both CAFs and tumor cells, activates Wnt and Notch pathways, supporting the fitness of metastasis-initiating breast cancer cells and their “seeding” at the metastatic site." (PMID 29112161, 2017). "In a mouse model, Tenascin-C knockdown dramatically inhibited lung metastasis and colonization by breast cancer cells." (PMID 26731558, 2016). "A high combined expression score of 5 stromal proteins, namely THBS1, TNC, FN, SPARC and α-SMA, in baseline untreated breast cancers, is associated with shorter survival, while their up-regulation after chemotherapy predicted for poor treatment response." (PMID 27487140, 2016). "TNC protein expression was up-regulated in breast cancer patients with progressive disease treated with either anthracyclin- or taxane-based monotherapy." (PMID 27487140, 2016). "α-SMA, TNC and SPARC, which represents the abundance of cancer-associated fibroblasts and extracellular matrix, have been linked to shorter survival in breast cancer in retrospective studies based on their gene or protein expression levels." (PMID 27487140, 2016). "Four marker genes (ID4, SOSTDC1, SLC26A2, TNC) relevant to drug activity to cisplatin on breast cancer cells were derived from the signature genes for breast cancers." (PMID 26824188, 2016). "The Tenascin-C-positive areas in macrometastases of breast cancer to the lungs were infiltrated with myofibroblasts and macrophages." (PMID 26731558, 2016). "Both observations are in accordance with the striking expression of tenascin C seen at sites of epithelial–mesenchymal interactions during development and at the invasive front of human breast cancer samples." (PMID 26539408, 2015). "Tenascin-C-rich stroma has been observed consistently adjacent to the epithelial cell nests of breast and other cancers; further, tenascin-C appears to play a role in initiating and sustaining lung colonization of breast cancer cells." (PMID 25837326, 2015). "This was consistent with immunohistochemical staining of human breast cancer samples, revealing tumor cell tenascin C expression in early malignant stages, and a strong reaction in stromal cells in advanced cirrhotic carcinomas." (PMID 26539408, 2015). "A further mediator of cell motility is tenascin C. By binding to either integrin αvβ1 or αvβ6, recombinant tenascin C induced a change in the morphology of the breast cancer cell line MCF-7 to a more mesenchymal phenotype." (PMID 26539408, 2015). "We discovered a breast cancer-specific set of genes including tenascin-C, which is regulated by Mkl1 in a SAP domain-dependent, serum response factor-independent manner and is strongly implicated in cell proliferation, cell motility and cancer." (PMID 24495796, 2014). "There is strong evidence that tenascin-C contributes to the metastatic behavior of breast cancer cells by providing a niche for their settlement in the lung." (PMID 24495796, 2014). "Tenascin-C was not only enriched in breast cancer tissue, but its high expression was part of a gene signature of breast cancers metastasizing to the lung." (PMID 24495796, 2014). "Tenascin-C is known to be expressed in metastatic niches, is highly induced in cancer stroma and promotes breast cancer metastasis to the lung." (PMID 24495796, 2014). "The relationship between VCAN and TNC has not been clearly understood yet, although a tissue co-localization of these glycoproteins has been detected in the peritumoural stroma in breast cancer." (PMID 25064447, 2014). "Of these, miR-335 was reported to suppress metastasis and migration by targeting SOX4 and tenascin C and inhibit tumor initiation in breast cancer." (PMID 23229728, 2013). "Interactions of the breast cancer cells with integrins, fibronectin, tenascin C, laminins, collagens, endoglin, hyaluronan, heparanase and proteoglycans can contribute to the metastatic process." (PMID 23343205, 2013).
breast cancer (continued). "Recently, breast cancer cells infiltrating the lungs were shown to support their own metastasis-initiating ability by expressing tenascin C (TNC)." (PMID 22482059, 2012). "The administration of NSAIDs suppresses the progression of breast cancer cells through downregulation of tenascin C expression." (PMID 22711317, 2012). "Tenascin-C is highly expressed in the majority of malignant solid tumors, including gliomas, and cancer of the breast, uterus, ovaries, prostate, colon, stomach, pancreas, lung, liver, skin and kidney." (PMID 23145140, 2012). "It is co-ordinately regulated together with other mesenchymal markers, such as the extracellular matrix molecule tenascin C, whose expression in human breast carcinomas correlates positively with ERBB2 over-expression and down-regulation of ER." (PMID 21713035, 2011). "Recent studies also showed that the expression of tenascin-C in invasion borders of early breast cancer significantly correlates with proliferative activity, higher risk of distant metastasis and local recurrence." (PMID 20454448, 2010). "Recently, both SOX4 and tenascin C were shown to enhance metastasis of breast cancer cells to the lung." (PMID 20419098, 2010). "We previously identified induction of two intermediate-sized TNC isoforms in breast cancers and showed that these isoforms can enhance tumour cell invasion; a similar change was demonstrated in ovarian carcinomas." (PMID 20678196, 2010). "We demonstrated that the TNC-14/AD1/16 isoform significantly increased breast cancer cell invasion and growth." (PMID 20678196, 2010). "Expression of tenascin-C was shown to be able to induce cell invasion through matrix metalloproteinase in breast cancer and glioma cells." (PMID 20454448, 2010). "A consistent feature of the stroma around many breast carcinomas is upregulation of the extracellular matrix glycoprotein tenascin-C (TNC)." (PMID 20678196, 2010). "Real-time PCR for endogenous TNC isoform expression was performed on a series of breast cancer cell lines." (PMID 19405959, 2009). "The ECM protein tenascin-C (TNC) is frequently up-regulated in breast cancer and we have previously identified two novel isoforms – one containing exon 16 (TNC-16) and one containing exons 14 plus 16 (TNC-14/16)." (PMID 19405959, 2009). "This suggests that tenascin C could be a crucial contributor to invasive transformation in breast cancer." (PMID 39716322, 2024). "TNC, COL18A1 and COL12A1 gene expression characterize fibroblasts known as ECM-CAF (Extracellular Matrix-Cancer Associated Fibroblasts) which participates in the aberrant remodeling of the extracellular matrix in breast cancer." (PMID 39239354, 2024). "Overexpression of TNC could be specifically detected and associated with immunosuppression and sever progression in various cancers, such as NSCLC, breast cancer and oral tongue squamous cell carcinoma." (PMID 36906534, 2023). "Additionally, α11 integrin/PDGFRβ+ CAFs respond to the stimulation and promotes invasion and metastasis via c-Jun N-terminal kinase (JNK)/TNC in breast cancer." (PMID 36906534, 2023). "Based on the ability of TNC to promote tumor development, the high expression of TNC in CAFs is an independent prognostic marker for multiple cancers, including breast cancer, bladder cancer, prostate cancer, CRC (especially stage II and III CRC), and pancreatic cancer." (PMID 37143134, 2023). "SAP-dependent expression of TNC correlates with shorter survival of breast cancer patients." (PMID 36102918, 2022). "Similarly, targeting TNC in a breast cancer progression model together with anti-PDL-1 treatment was also more potent in reducing metastasis than either treatment alone." (PMID 36102918, 2022). "Our novel observation regarding reduced PDGFRβ and TNC expression in α11-deficient mouse skin tumors is in line with these previous findings on breast cancer and suggests that the α11/PDGFRβ/TNC axis may promote also skin carcinogenesis." (PMID 36003785, 2022).
breast cancer (continued). "In addition, THBS1, RARRES1, and TNC levels correlate with OSMR expression in breast cancer clinical samples." (PMID 35192545, 2022). "Furthermore, TNC expression in breast cancer cells was unaffected by treatment with EC-CM or recombinant vascular niche factors." (PMID 35469015, 2022). "Interestingly, TNC has been demonstrated to induce phenotypic changes of fibroblasts to myofibroblasts in human breast cancer." (PMID 34020624, 2021). "In human breast cancer specimens, TNC is co-expressed with the mesenchymal marker vimentin." (PMID 32817625, 2020). "Another glycoprotein, Tenascin C, has also been shown to contribute to breast cancer metastasis." (PMID 32455252, 2020). "Soluble tenascin C induces EMT in different breast cancer cell lines through alpha V integrin." (PMID 32340328, 2020). "Similar mechanisms observed in bone-tropic breast cancer metastases suggests that Tenascin-C also supports metastatic outgrowth in bone metastases and may contribute to the metastasis of lung cancer cells to the bone microenvironment." (PMID 33014869, 2020). "mRNA level of TNC was highly expressed in breast cancer tissue (BRCA)." (PMID 32817625, 2020). "It had been reported that the elevated expression of TNC depended on a malignancy in the tumor stroma of some malignancies, including oral cancer, sarcoma, breast cancer, and colon cancer, squamous cell carcinoma chondrosarcoma, breast cancer and colon cancers." (PMID 31140150, 2019). "Similar to tenascin-C, which is part of the lung-metastatic niche for breast cancer cells, evidence emerged recently that tenascin-W is a component of the congenial metastatic niche in breast cancer cells disseminating to bone." (PMID 31032255, 2019). "Importantly, disruption of either JNK activity or expression of SPP1 or TNC sensitizes mammary tumors and metastases to chemotherapy, suggesting a potentially useful combinatorial treatment strategy to target metastatic breast cancer." (PMID 30190333, 2018). "Notably, inhibition of JNK signaling or repression of SPP1 or TNC expression can sensitize mammary tumors and lung metastases to chemotherapy." (PMID 30190333, 2018). "Moreover, our results provide rationale for considering JNK inhibition as a strategy to simultaneously repress the expression of SPP1 and TNC and thus improve therapeutic responses of breast cancer to chemotherapy." (PMID 30190333, 2018). "For instance, tenascin C promotes Notch and Wnt signaling, inducing breast cancer cell metastasis to the lungs in mice and positively correlating with aggressiveness and poor survival in breast cancer patients." (PMID 29883428, 2018). "DDR1 activity could also promote homing of disseminated tumour cells in the liver upon collagen deposition to support β‐catenin‐dependent cell survival, as documented for other extracellular matrix components, such as tenascin C in metastatic breast cancer." (PMID 29438985, 2018). "Tenascin-C is a stromal protein that has been reported to be more highly expressed in invasive breast carcinomas and has also been shown to support lung metastatic niche formation from breast cancer cells." (PMID 28187162, 2017). "Thus, up-regulation of THBS1, TNC, FN, SPARC and α-SMA following neoadjuvant chemotherapy was associated with chemotherapy resistance in breast cancer patients." (PMID 27487140, 2016). "miR-335 appears to control growth by blocking cell proliferation by targeting certain genes; e.g., RASA1 in rat epididymal development, SP1 and Bcl-w in non-small cell lung cancer, SOX4 and TNC in breast cancer, ROCK1, MAPK1, and LRG1 in neuroblastoma, and Rb1 in U2OS osteosarcoma cells." (PMID 26204513, 2015). "Increased expression of tenascin-C has been also found in the stroma of various cancers and its expression is predictive of local recurrence, metastatic dissemination of cancer cells and anti-cancer treatment responsiveness in breast cancer." (PMID 26581390, 2015).
breast cancer (continued). "Moreover, tenascin-C and periostin are both expressed in the hair follicle stem cell niche in murine skin and are crucial for metastatic breast cancer stem cells colonizing the lung." (PMID 25301723, 2014). "Tenascin C is an extracellular matrix glycoprotein often upregulated in breast cancers." (PMID 22711317, 2012). "The importance of this stromally derived tenascin-C is demonstrated by absence of lung metastasis formation when breast cancer cells are implanted into tenascin-C-deficient mice." (PMID 22699312, 2012). "In addition, miR-335 and miR-126 are also reported to be associated with the ability of breast cancer cells to metastasize to the lung and bone by directly suppressing the ECM component tenascin c (TNC)." (PMID 22200848, 2012). "The mechanism by which TNC-16 and TNC-14/16 promote breast cancer cell invasion and proliferation is unclear, although it does appear to require direct interaction between the tumour cell and the protein, because the pro-invasive effect was blocked by TNC antibody." (PMID 19405959, 2009). "We previously have shown that, in addition to a quantitative change in TNC in breast cancer, there is a consistent change in the pattern of TNC isoform expression, with induction of two additional isoforms – TNC-16 and TNC-14/16 – rarely detected in normal resting breast." (PMID 19405959, 2009). "Spliced tenascin-C has important roles in tumor progression of breast cancer." (PMID 16893473, 2006). "For example, FN, tenascin-C (TNC), and type I collagen were described to act as pro-metastatic cues, or in patients with breast cancer it was reported that an ECM signature consisting of fibrinogen, elastin, FN, and vitronectin predicts the outcome of the disease." (PMID 38660622, 2024). "Importantly, the role of tenascin-C as a regulator of TGFβ signaling appears to be central to its effects on dormancy in breast cancer cells colonizing the lungs and parallels may be drawn to primary lung tumors or intrapulmonary metastases." (PMID 33014869, 2020). "Further studies are warranted to dissect the mechanisms by which Tenascin-C affects the progression and dissemination of lung tumor cells, with particular attention to where these mechanisms converge with and diverge from its more established role in breast cancer metastasis." (PMID 33014869, 2020). "Moreover, co-expression of TNC and vimentin might induce mesenchymal-like phenotype in breast cancer cell." (PMID 27391030, 2016). "The almost universal and high level of expression of these isoforms in breast carcinomas coupled with their largely tumour-restricted distribution make them a plausible therapeutic target, a strategy that already is being employed for tumour-restricted TNC isoforms in other systems." (PMID 19405959, 2009). "In breast cancer, MAPK8 activation enhances the expression of ECM components such as osteopontin and tenascin C, which drive metastasis and therapy resistance by reinforcing the chemoresistant metastatic niche." (PMID 40468448, 2025). "In breast cancer, FSP1-positive CAFs promote metastasis by secreting VEGF-A and tenascin-C, with higher expression in ILC than NST." (PMID 40230452, 2025). "This aligns with observations in breast cancer, where decreased miR-335 expression correlates with poor survival due to its inhibitory effect on metastasis via targeting SOX4 and Tenascin-C (TNC)." (PMID 38542153, 2024). "Cav-1 in exocrine bodies derived from Breast cancer (BC) can be used as signal molecules to promote the secretion of tenascin-C in lung fibroblasts and lead to the deposition of ECM, which mediates intercellular communication and regulates premetastatic niche (PMN) before lung metastasis." (PMID 37978384, 2023). "Several ECM components, such as collagens, hyaluronan (HA), Fibronectin (FN), and Tenascin-C (TNC) play important roles in early PMN and promote breast cancer metastasis." (PMID 37153744, 2023).
breast cancer (continued). "Together, these data reveal a positive correlation between the expression of TNC and CCL2 in HER2+ breast cancer and show that TNC is required to maintain high levels of CCL2 expression in tumor cells." (PMID 37176074, 2023). "For example, Tenascin C (TNC) and periostin (POSTN) play important roles in both the survival and maintenance of stem cell functions of disseminated breast cancer cells and are required for metastatic outgrowth." (PMID 35737114, 2022). "Accumulating evidence has suggested that TNC can promote “EMT-like” changes in different cancers, including breast cancer, gastric cancer, colorectal cancer, pancreatic ductal adenocarcinoma, and nasopharyngeal carcinoma." (PMID 36033448, 2022). "TNC enhances the WNT pathway and thereby cancer cell proliferation, via its positive regulator Musashi homologue 1 (MSI1) and NOTCH signalling in breast cancer cells." (PMID 35260891, 2022). "Tenascin-C (TN-C) is an important extracellular matrix (ECM) component, which has been reported to be involved in other types of cancer, such as breast cancer." (PMID 35246056, 2022). "For instance, Oskarsson and co-workers have proved that ECM proteins like Tenascin-C (TNC) and Versican (VCAN) play a critical role during the earliest stage of breast cancer metastasis to the lungs." (PMID 33418894, 2021). "They demonstrated that constitutive activation of JNK signaling in a human breast cancer cell line promotes significant upregulation of gene expression of ECM proteins such as SPP1 (osteopontin) and TNC (tenascin C)." (PMID 32283767, 2020). "TNC is the main ECM protein of various tumors and its over-expression is repeatedly observed in breast cancer cells both in vitro and in vivo, indicating a role for this extracellular matrix glycoprotein in neoplastic pathology." (PMID 32817625, 2020). "This is similar to investigations of the pro-metastatic role of KDM5A in breast cancer, where KDM5A was found to upregulate expression of TNC (also identified as a KDM5A-dependent gene in our studies) via a demethylase-independent mechanism." (PMID 33196691, 2020). "For example, in the calcium signaling pathway, we found that the sub-pathway TnC, PHK, CAMK, NOS, ADCY, FAK2, IP3-3K was only active in breast cancer liver metastasis." (PMID 31557971, 2019). "In this study, we show that activation of the stress‐induced JNK signaling pathway promotes breast cancer progression to metastasis by upregulating SPP1 and TNC, two ECM proteins that normally reside within stem cell niches." (PMID 30190333, 2018). "Moreover, chemotherapy treatment leads to JNK‐mediated induction of SPP1 and TNC in metastatic breast cancer cells, indicating that, apart from its intended function as a cytotoxic agent, chemotherapy may actually reinforce the establishment of a metastatic niche via the JNK signaling pathway." (PMID 30190333, 2018). "Given the important contributions of the ECM in breast cancer biology, protein expression levels of specific ECM components such as fibronectin and tenascin C are known prognostic markers for poor overall patient survival." (PMID 27556857, 2016). "Despite the difference in the organs involved and cancer types, our result is highly consistent with the results of previous studies in which patients with breast cancer and HCC with high expression levels of Tenascin-C showed a poor survival prognosis." (PMID 26731558, 2016). "It has been reported that miR-335 suppresses breast cancer metastasis by targeting SOX4 and Tenascin C, small cell lung cancer metastasis by targeting IGF1R and RANKL, and induces apoptosis of breast cancer cells by regulating ERα, IGF1R, SP1, and ID4." (PMID 26098312, 2015). "Silencing of HMGA2 in the invasive breast cancer cell model MDA-MB-231 affected, in addition to E-cadherin, the expression of invasive genes, such as MMP2 and TNC, and reduced the rate of motility and infiltration of cells through matrigel." (PMID 25492890, 2015).